H2AC18 (H2A clustered histone 18)
Description:
Core component of nucleosome. Nucleosomes wrap and compact DNA into chromatin, limiting DNA accessibility to the cellular machineries which require DNA as a template. Histones thereby play a central role in transcription regulation, DNA repair, DNA replication and chromosomal stability. DNA accessibility is regulated via a complex set of post-translational modifications of histones, also called histone code, and nucleosome remodeling.
Synonyms: H2AFO; HIST2H2AA; HIST2H2AA3; H2A.2; H2A/q; H2A; H2A/O; H2a-615
Tractability: Small molecule: a structure with a bound ligand is known. PROTAC: UniProt records ubiquitination sites on it; ubiquitination databases record sites on it.
Gene: Protein-coding gene on chromosome 1 (149,842,218 to 149,842,750, reverse strand). Ensembl gene ENSG00000288825.
Subcellular location: Nucleus; Chromosome
Subcellular location (Human Protein Atlas): Nucleoplasm
Pathways (Reactome):
Gene expression (Transcription): B-WICH complex positively regulates rRNA expression; DNA methylation; ERCC6 (CSB) and EHMT2 (G9a) positively regulate rRNA expression; MLL4 and MLL3 complexes regulate expression of PPARG target genes in adipogenesis and hepatic steatosis; NoRC negatively regulates rRNA expression; PRC2 methylates histones and DNA; RNA Polymerase I Promoter Escape; RNA Polymerase I Promoter Opening; RUNX1 regulates genes involved in megakaryocyte differentiation and platelet function; RUNX1 regulates transcription of genes involved in differentiation of HSCs; Regulation of endogenous retroelements by KRAB-ZFP proteins; Regulation of endogenous retroelements by Piwi-interacting RNAs (piRNAs); Regulation of endogenous retroelements by the Human Silencing Hub (HUSH) complex; SIRT1 negatively regulates rRNA expression; Transcriptional regulation by small RNAs
Chromatin organization: CHD1 and CHD2 subfamily; CHD6, CHD7, CHD8, CHD9 subfamily; ChAHP complex assembly; HATs acetylate histones; HDACs deacetylate histones; Interaction of NuRD complexes with transcription factors; NuRD complex assembly; RMTs methylate histone arginines
Cell Cycle: Condensation of Prophase Chromosomes; Deposition of new CENPA-containing nucleosomes at the centromere; Inhibition of DNA recombination at telomere; Packaging Of Telomere Ends
DNA Repair: Cleavage of the damaged purine; Cleavage of the damaged pyrimidine; Recognition and association of DNA glycosylase with site containing an affected purine; Recognition and association of DNA glycosylase with site containing an affected pyrimidine
Disease: Defective pyroptosis; Dengue Virus-Host Interactions; HCMV Early Events; HCMV Late Events
Metabolism of proteins: Amyloid fiber formation; Metalloprotease DUBs; UCH proteinases; Ub-specific processing proteases
Signal Transduction: Activated PKN1 stimulates transcription of AR (androgen receptor) regulated genes KLK2 and KLK3
and 15 more pathways
Gene Ontology:
Molecular function: protein binding; structural constituent of chromatin; DNA binding; protein heterodimerization activity
Biological process: heterochromatin formation
Cellular component: extracellular exosome; nucleoplasm; nucleus; nucleosome; chromosome
Homologues: Orthologues: pig H2AC18 (100% identical), Drosophila melanogaster His2A:CG31618 (85% identical), Drosophila melanogaster His2A:CG33808 (85% identical), Drosophila melanogaster His2A:CG33814 (85% identical), Drosophila melanogaster His2A:CG33817 (85% identical), Drosophila melanogaster His2A:CG33820 (85% identical), Drosophila melanogaster His2A:CG33823 (85% identical), Drosophila melanogaster His2A:CG33826 (85% identical), Drosophila melanogaster His2A:CG33829 (85% identical), Drosophila melanogaster His2A:CG33832 (85% identical), Drosophila melanogaster His2A:CG33835 (85% identical), Drosophila melanogaster His2A:CG33838 (85% identical), and 9 more. Paralogues in human: H2AC19 (100% identical), H2AC11 (98% identical), H2AC13 (98% identical), H2AC15 (98% identical), H2AC16 (98% identical), H2AC17 (98% identical), H2AC6 (98% identical), H2AC20 (98% identical), H2AC25 (98% identical), H2AC7 (98% identical), H2AC12 (97% identical), H2AC4 (97% identical), and 15 more.